FREM2 (FRAS1 related extracellular matrix 2)
Diseases named in the same sentence as FREM2 in open-access papers (continued):
Sharing a sentence is not in itself a finding about the gene and the disease.
tumor (13 papers, 2019 to 2025). "It was previously shown that the high FREM2 expression in tumor tissues, and mutations in FREM2 exhibited an association with poorer prognosis of cancer patients." (PMID 36439501, 2022). "According to the age, gender, tumor stage, and risk score of COAD patients with FREM2 mutations, univariate Cox analysis and multivariate Cox analysis were performed to construct a clinical prediction model." (PMID 35252356, 2022). "Further analysis of COAD tissue samples showed that FREM2 was highly expressed in tumor tissues compared to normal tissues." (PMID 35252356, 2022). "The low expression level of FREM2 gene was also significantly correlated with advanced pathological stage (p = 2E-17), high pathological grade (p = 2.1E-20) and tumor metastasis status (p = 5.9E-06)." (PMID 36249757, 2022). "We investigated how the expression level of the FREM2 gene or activation of FREM2 pathways was connected with the LGG or GBM status of a tumor in the available datasets." (PMID 34439271, 2021). "Finally, 30 samples of CRC patients were collected for immunohistochemical staining to analyze the FREM2 expression levels, which showed that FREM2 was highly expressed in tumor tissues." (PMID 35252356, 2022). "Besides, FRAS1, FREM1 and FREM2 mRNA and protein expressions were correlated with the clinicopathological characteristics (pathological stage, grade and tumor metastasis status) of the patients with KIRC." (PMID 36249757, 2022). "In addition, FREM2 expression decreased as the tumor stage advanced." (PMID 36439501, 2022). "In addition, since FREM2 mutation was associated with immune infiltration, we analyzed its association with the expression levels of PDCD1, CD274, CTLA4, LAG3, TIGIT, and HAVCR2, which are important immune checkpoints responsible for tumor immune escape." (PMID 35252356, 2022). "Some DEGs like FREM2, ANXA2 and GPC4 revealed common enrichment in LE/IT tumor regions across GBM patient samples compared to the overall downregulation of the OPC/OL marker MBP, the neural marker NTRK2, and the ECM glycoprotein EDIL3." (PMID 41366031, 2025). "The relative expression of KISS1, FREM2, and ECM1 were in the pyramidal pattern, implying that maximal expression was in the tumor area." (PMID 38062443, 2023). "The expression levels of TLL1, HMCN2, FREM2 and MMP17 were significantly higher in normal ovarian tissues than in tumour tissues." (PMID 37388244, 2023). "We investigated how the expression levels of CRNDE, FREM2, and SPRY1 genes were connected with the “old” and “new” tumor types." (PMID 36613601, 2022). "The expression levels of FRAS1, FREM1 and FREM2 in both KIRC and non-tumor tissues were also measured by qRT-PCR verification, which confirmed the expression profiles of FRAS1/FREM family." (PMID 36249757, 2022). "In addition, the expression levels of FREM2 in COAD tissues was analyzed using the HPA database, and it was found that FREM2 was highly expressed in tumor tissues." (PMID 35252356, 2022). "To explore whether FRAS1, FREM1 and FREM2 were involved in the process of immune infiltration in KIRC, we employed TIMER 2.0 to exhibit the landscape of FRAS1/FREM correlating with tumor purity and various immune infiltrates in human cancers." (PMID 36249757, 2022). "Interestingly, FRAS1 and FREM2 expression decreased in the stage I and stage II patients who had a high propensity to metastasise, which means FRAS1 and FREM2 could be tumor metastasis markers of KIRC." (PMID 36249757, 2022).
cancer (12 papers, 2015 to 2025). A tumor composed of atypical neoplastic, often pleomorphic cells that invade other tissues. "FREM2 RNA expression levels were analyzed in different TCGA and experimental validation cohorts and showed that FREM2 has low overall cancer specificity." (PMID 39982223, 2025). "Our study explored the relationship between FRAS1, FREM1 and FREM2 promoter methylation and cancer for the first time." (PMID 36249757, 2022). "The mRNA expression levels of FRAS1, FREM1 and FREM2 were analyzed in Oncomine over a cancer-wide range." (PMID 36249757, 2022). "Our in-silico validation took into consideration a large number of cancer types, and showed that median FREM2 and SPRY1 expression were comparable among the different cancer types." (PMID 31357584, 2019). "We selected those genes with functions known to be associated with cancer of which there were 12—SNVs: NOTCH2, PIK3CG, IL2RB, BAI3, FREM2 and RERE; indels: UTRN, CDHR3, NCOA5, CABYR, HOTAIR and FOLH1." (PMID 26017033, 2015). "Finally, we analyzed the protein expression of FREM2 in pan-cancer and COAD using UALCAN and HPA databases and found that FREM2 was highly expressed in COAD, which was consistent with the results of immunohistochemistry." (PMID 35252356, 2022). "The information about FREM2 expression in cancer is rather scarce." (PMID 33187334, 2020). "Indeed, two other genes in the FRAS/FREM family, FRAS1 and FREM2, have been shown to be related with the occurrence and progression of certain carcinomas." (PMID 33058542, 2020). "However, other genes of the same gene family as FREM2, namely FRAS1 and FREM1, were recently reported as cancer-related genes." (PMID 34439271, 2021). "On the other hand, there was no differential expression of NCL, FREM2, and SPRY1 genes in the sEVs of cancer cell lines and astrocytes." (PMID 33187334, 2020).
genetic diseases (2 papers, 2024 to 2025). "This is consistent with the fact that individuals with HNF1B mutations do have kidneys, in contrast to certain other human genetic diseases (e.g., FRAS1 or FREM2 mutations) where organogenesis fails to initiate." (PMID 38788724, 2024).
infection (1 paper, 2023). The state of being infected such as from the introduction of a foreign agent such as serum, vaccine, antigenic substance or organism. "We confirmed selective cytoplasmic downregulation of FREM2 mRNA expression upon infection by cell fractionation and RT-qPCR." (PMID 36603024, 2023).
FREM2 also shares sentences with these, for which no sentence is quoted: gliosarcoma (2 papers); astrocytomas (1); brain cancer (1); breast invasive carcinoma (1); connective tissue disorder (1); dysplasia (1); Ellis-van Creveld syndrome (1); heart malformations (1); Hypergonadotropic hypogonadism (1); Manitoba oculotrichoanal syndrome (1); Mayer-Rokitansky-Küster-Hauser syndrome (1); microtia (1); Noonan syndrome (1); oligoastrocytoma (1); oligodendroglioma (1); osteogenesis imperfecta (1); Primary amenorrhea (1); rectal cancer (1); syndactyly (1); urothelial carcinoma (1); uterine corpus endometrial carcinoma (1).